ZNF609 (zinc finger protein 609)
Diseases named in the same sentence as ZNF609 in open-access papers (continued):
Sharing a sentence is not in itself a finding about the gene and the disease.
rhabdomyosarcoma (5 papers, 2019 to 2024). A rare aggressive malignant mesenchymal neoplasm arising from skeletal muscle. "Circ-ZNF609 is frequently discovered in the cytoplasm of human cells, including myoblasts, rhabdomyosarcoma, and cholangiocarcinoma." (PMID 38472174, 2024). "circ-ZNF609 was found to have functions in myoblast, rhabdomyosarcoma, and vascular endothelium via acting as miRNA sponges or capable of translation." (PMID 35474903, 2022). "By contrast, circ‐ZNF609 expression promotes cell proliferation in rhabdomyosarcoma, highlighting circ‐ZNF609 as a new regulator of cell proliferation‐related pathways that abrogates p‐Akt proteasome‐dependent degradation." (PMID 34672397, 2021). "To deepen our knowledge about circ-ZNF609 role in cell cycle regulation, we studied its expression and function in rhabdomyosarcoma (RMS), a pediatric skeletal muscle malignancy." (PMID 30670781, 2019). "Furthermore, because of circ-ZNF609 ability to promote myoblast proliferation, we studied its expression, function, and effects on the transcriptome in rhabdomyosarcoma (RMS), a pediatric skeletal muscle malignancy." (PMID 30670781, 2019). "Recently, it was proven that the circRNA circ-ZNF609, which requires YTHDC1 for its back-splicing reaction, increases in pathological conditions, such as rhabdomyosarcoma." (PMID 35563766, 2022).
cholangiocarcinoma (4 papers, 2021 to 2025). A carcinoma that arises from the intrahepatic biliary tree (intrahepatic cholangiocarcinoma) or from the junction, or adjacent to the junction, of the right and left hepatic ducts (hilar cholangiocarcinoma). "The qRT-PCR data showed that the circ-ZNF609 expression was higher in cholangiocarcinoma tissues than adjacent normal tissues." (PMID 34898474, 2021). "In the present study, circ-ZNF609 expression was found to be significantly higher in cholangiocarcinoma tissues and cells than in normal adjacent tissues and cells for the first time." (PMID 34898474, 2021). "In this study, circ-ZNF609 was discovered as a novel circRNA highly expressed in cholangiocarcinoma for the first time." (PMID 34898474, 2021). "And the dysregulation of circ-ZNF609 was intimately associated with TNM stage, lymph node invasion and prognosis of patients with cholangiocarcinoma." (PMID 34898474, 2021). "Circ-ZNF609 was expressed highly in cholangiocarcinoma cells (TFK-1, RBE, CCLP-1, QBC939) compared to normal biliary cell (HIBEC), and follow-up experiments were performed applying CCLP-1 and QBC939." (PMID 34898474, 2021). "Circ-ZNF609 can promote the cholangiocarcinoma cells proliferation, migration and invasion in vitro, it can also catalyze the xenograft growth in vivo." (PMID 34898474, 2021). "Correlation between circ-ZNF609 expression and clinicopathological characteristics of cholangiocarcinoma patients." (PMID 34898474, 2021). "Overall, YY1/eIF4A3/circ-ZNF609/miR-432-5p/LRRC1 have a significant role in progression of cholangiocarcinoma, and circ-ZNF609 is expected to become a novel biomarker for targeted therapy and prognosis evaluation of cholangiocarcinoma." (PMID 34898474, 2021). "MiR-432-5p had low expression in the cholangiocarcinoma tissues and cells, and was negatively correlated with circ-ZNF609 expression." (PMID 34898474, 2021). "The promoting effect of circ-ZNF609 on cholangiocarcinoma is achieved via oncogene LRRC1 up-regulation through targeting miR-432-5p by endogenous competitive RNA mechanism." (PMID 34898474, 2021). "The results of cell viability assay (CCK-8, EdU, colony formation) indicated that down-regulation of circ-ZNF609 inhibited the cholangiocarcinoma cells proliferation." (PMID 34898474, 2021). "Moreover, circ-ZNF609 promotes tumor progression in cholangiocarcinoma by upregulating LRRC1 via targeting miR-432-5p, leading to increased proliferation, migration, and invasion." (PMID 40227650, 2025). "In addition, anomalous upregulation of circ-ZNF609, lymph node invasion and advanced TNM stage were independent risk factors for unfavorable prognosis in patients with cholangiocarcinoma." (PMID 34898474, 2021). "Nevertheless, the association of circ-ZNF609 with cholangiocarcinoma has not been investigated, so it was necessary to explore the clinical values and biological functions of circ-ZNF609 in cholangiocarcinoma." (PMID 34898474, 2021). "In summary, circular RNA ZNF609 is involved in the cholangiocarcinoma development, suggesting that it may be a prospective target for therapeutic and prognostic evaluation." (PMID 34898474, 2021). "This present study confirmed that circ-ZNF609 had a carcinogenic effect in cholangiocarcinoma." (PMID 34898474, 2021). "It was further experimentally proved that circ-ZNF609 could facilitate the tumor cells proliferation, migration and invasion in cholangiocarcinoma." (PMID 34898474, 2021). "The circ-ZNF609 expression is connected with the advanced TNM stage, lymphatic invasion and survival time in cholangiocarcinoma patients, and can be used as an independent prognostic factor for the patients." (PMID 34898474, 2021). "The correlation between circ-ZNF609 and cholangiocarcinoma, on the other hand, had not been investigated." (PMID 34898474, 2021).
gastric cancer (4 papers, 2021 to 2022). A primary or metastatic malignant neoplasm involving the stomach. "For instance, circ-ZNF609 facilitated carcinogenesis of gastric cancer cells through the inhibition of miRNA-145-5p expression." (PMID 35135416, 2022). "It acted as a sponge of miR-483-3p, upregulated the expression of cell-promoting factor cyclin-dependent kinase 6 (CDK6), and promoted the proliferation and migration of gastric cancer cells through the circ-ZNF609/miR-483-3p/CDK6 axis." (PMID 35938040, 2022). "It has been reported that circular RNA ZNF609 contributes progression of gastric cancer via repressing miRNA-145-5p." (PMID 34520391, 2021).
hepatocellular carcinoma (3 papers, 2021 to 2022). A malignant tumor that arises from hepatocytes. "As in hepatocellular carcinoma, circ-ZNF609 inhibits miR-15a-5p/15b-5p expression and then elevates GLI2 (a key protein molecule concerning the Hedgehog pathway) expression, activating the Hedgehog pathway to promote hepatocellular carcinoma (HCC) proliferation and metastasis." (PMID 35938040, 2022).
lung carcinoma (3 papers, 2021 to 2023). "ZNF609 contributes to proliferation of lung cancer cells by regulating miR-1224-3p/ETV1 axis." (PMID 34520391, 2021).
Duchenne muscular dystrophy (2 papers, 2021 to 2025). Duchenne muscular dystrophy (DMD) is a neuromuscular disease characterized by rapidly progressive muscle weakness and wasting due to degeneration of skeletal, smooth and cardiac muscle. "The finding that circ-ZNF609 can be translated into a functional protein has broadened our understanding of circRNA roles in Duchenne muscular dystrophy." (PMID 41322400, 2025). "The pro-proliferative effect of elevated circ-ZNF609 in Duchenne muscular dystrophy may be mediated by its influence on cell cycle regulators (e.g., CDK1, Cyclin A2)." (PMID 41322400, 2025). "Interestingly, circ-ZnF609 was also identified as a circRNA regulating muscle differentiation in mice and humans, and its expression is altered in Duchenne muscular dystrophy (DMD) myoblasts." (PMID 34250050, 2021).
acute kidney injury (1 paper, 2025). Sudden and sustained deterioration of the kidney function characterized by decreased glomerular filtration rate, increased serum creatinine or oliguria. "Another recent study found that circ-ZNF609 encodes ZNF609-250aa, a 250-aa novel protein that exacerbates acute kidney injury (AKI) by inhibiting autophagic flow and inducing apoptosis via an AKT/mammalian target of rapamycin (mTOR)-dependent mechanism." (PMID 41181701, 2025).
colorectal cancer (1 paper, 2022). A primary or metastatic malignant neoplasm that affects the colon or rectum. "Emerging evidence has shown the vital role of circ-ZNF609 in colorectal cancer development and progression." (PMID 35938040, 2022).
coronary artery disease (1 paper, 2021). "Importantly, the authors detected a high level of circ‐ZNF609 expression in clinical samples from patients with diabetes, hypertension and coronary artery disease, suggesting that targeted regulation of circ‐ZNF609 expression is a potential approach for the treatment of vascular dysfunction." (PMID 34697887, 2021).
COVID-19 (1 paper, 2022). A disease caused by infection with severe acute respiratory syndrome coronavirus 2. "It is a promising research direction to develop a circRNA-based vaccine, by integrating an antigen-encoding sequence of COVID-19 into circ-ZNF609." (PMID 35938040, 2022). "The internal ribosomal entry site of circ-ZNF609 confers the translational function, making it possible to express the antigen of COVID-19." (PMID 35938040, 2022). "The possible function of circ-ZNF609 in the prevention of the COVID-19 epidemic was also explored." (PMID 35938040, 2022).
esophageal cancer (1 paper, 2025). A primary or metastatic malignant neoplasm involving the esophagus. "In Esophageal Cancer high levels of exosomal circZNF609 promote metastasis and angiogenesis, partly by regulating the circ-ZNF609/miR-150-5p/VEGFA axis and the HuR/ZO-1 axis." (PMID 41301888, 2025).
glaucoma (1 paper, 2021). Increased pressure in the eyeball due to obstruction of the outflow of aqueous humor. "Silencing of circ‐ZNF609 inhibited retinal RGC proliferation and glial cell activation and promoted RGC survival in glaucoma." (PMID 34697887, 2021).
ischemia (1 paper, 2022). A hypoperfusion of the BLOOD through an organ or tissue caused by a PATHOLOGIC CONSTRICTION or obstruction of its BLOOD VESSELS, or an absence of BLOOD CIRCULATION. "Currently, functional study on circ-ZNF609 in vivo is conducted by regulating the expression of circ-ZNF609 before ischemia injury happens." (PMID 35474903, 2022).
melanoma (1 paper, 2022). A malignant, usually aggressive tumor composed of atypical, neoplastic melanocytes. "Comet assays showed that the tail length was elevated and the expression level of γH2AX variant histone (γH2AX) was increased after circ-ZNF609 depletion, suggesting that circ-ZNF609 inhibited the DNA damage in melanoma." (PMID 35938040, 2022). "As stated, circ-ZNF609-mediated DNA damage plays an important role in the development of melanoma." (PMID 35938040, 2022). "Knocking down circ-ZNF609 could inhibit the proliferation, migration, and invasion of melanoma cell lines, reduce cell survival rate, and promote apoptosis." (PMID 35938040, 2022).
muscular dystrophy (1 paper, 2022). Muscular dystrophy (MD) refers to a group of more than 30 genetic diseases characterized by progressive weakness and degeneration of the skeletal muscles that control movement. "circ-ZNF609 is associated with muscular dystrophy in mice and humans and has been shown to regulate myoblast proliferation." (PMID 35711944, 2022).
myocardial ischemia (1 paper, 2022). A disorder of cardiac function caused by insufficient blood flow to the muscle tissue of the heart. "After cardiac ischemia and 4 weeks of remodeling (chronic ischemic HF), circ-ZNF609 was significantly increased in the heart tissue from surgery-operated mice in contrast to the sham control." (PMID 35474903, 2022). "Here, we report that circ-ZNF609 is upregulated during myocardial ischemia/reperfusion (I/R) remodeling." (PMID 35474903, 2022). "Here, we explored the regulatory role of circ-ZNF609 in myocardial ischemia/reperfusion (I/R) injury by using murine together with neonatal rat cardiomyocyte (NRCM) models." (PMID 35474903, 2022).
renal fibrosis (1 paper, 2022). A final common manifestation of a wide variety of chronic kidney diseases characterized by glomerulosclerosis and tubulointerstitial fibrosis. "The expression of circ-ZNF609 was positively correlated with the degree of podocyte destruction and renal fibrosis, but miR-615-5p was negatively correlated with circ-ZNF609." (PMID 35938040, 2022).
thyroid cancer (1 paper, 2022). "However, the role of circ-ZNF609 in the occurrence and metastasis of thyroid cancer is still needed for further exploration." (PMID 35135416, 2022).
cancer (14 papers, 2020 to 2025). A tumor composed of atypical neoplastic, often pleomorphic cells that invade other tissues. "ZNF609's transcript forms a covalently closed loop structure through back‐splicing, which regulates the cell cycle transition in cancer cells." (PMID 40017443, 2025). "Here, we identified Circ-ZNF609, a circular RNA that is transferable between cancer cells and stromal cells." (PMID 38472174, 2024). "Further mechanistic investigation revealed that miR-514a-5p was sponged by circ-ZNF609 and its silencing had inverse effects on TP cell proliferation and metastasis, and cancer growth in xenograft mice model." (PMID 35135416, 2022). "The following content describes the molecular mechanisms of circ-ZNF609 in human cancers, in order by cancer names." (PMID 35938040, 2022). "FOXP4 (Forkhead box P4) majorly reported in many cancers, is also regulated by circ-ZNF609 through sponging mir-138-5p in renal carcinoma, resulting in the downregulation of cell proliferation and invasion processes." (PMID 35223470, 2022). "Taken together, it can be concluded that Circ-ZNF609 is upregulated in different cancers, and its downregulation can inhibit cancer progression." (PMID 35223470, 2022). "In human diseases, it exerts functions through the circ-ZNF609-miRNA-mRNA network, and circ-ZNF609 knockdown or overexpression of miRNA will inhibit the malignant phenotype of cancers." (PMID 35938040, 2022). "Circ-ZNF609, a new-found circRNA homologous to ZNF609 mRNA, has exhibited tumor-promoting effects on the progressions of multiple types of cancers." (PMID 35135416, 2022). "We found that the expression of circ-ZNF609 in various cancer tissues was higher than in adjacent normal tissues and dysregulation in nontumor diseases." (PMID 35938040, 2022). "circ‐ZNF609 can act as ceRNA to regulate several target genes via sponging different miRNAs, so as to participate in the initiation and development of cancers." (PMID 34697887, 2021). "In vitro experiments showed that knockout of circ‐ZNF609 effectively suppressed the activity, migration and invasion of cancer cells." (PMID 34697887, 2021). "It has previously been reported that circ-ZNF609 could modulate cancer progression through sponging miRNAs." (PMID 35135416, 2022). "Circ-ZNF609 (ID: hsa_circ_0000615 in circBase), located at chr15: 64,791,491–64,792,365, has been reported to exert important biological roles in promoting the tumorigenesis and metastasis of multiple types of cancers." (PMID 35135416, 2022). "Further study showed that circ‐ZNF609 could regulate Gli1 expression through miR‐150‐5p, thus affecting cancer metastasis." (PMID 34697887, 2021). "Circ-ZNF609 knockdown dramatically inhibits cancer cell proliferation, invasion, and metastasis." (PMID 32019587, 2020). "The correlation of ZNF609, miR-378b, and SLC2A1 and their function in other cancers should be explored by more investigations." (PMID 34520391, 2021). "In a similar finding, a recent study found high expression of circ‐ZNF609 in RCC cell lines, which accelerate cancer cell invasion and proliferation." (PMID 32729666, 2020). "However, 50 transcription factors displayed similar interactions with SWI/SNF in the two cancer types, such as several zinc-finger transcription factors (ZNF512, ZNF598, ZNF609, ZNF687, and ZNF709), CTCF, ELF2, and YBX1, indicating shared gene regulation networks." (PMID 40988026, 2025). "Therefore, we summarized the role of circ-ZNF609 in nontumorous diseases but not only in human cancers here." (PMID 35938040, 2022).
tumor (12 papers, 2019 to 2025). "Adding miR-138-5p inhibitor or overexpression of SIRT7 partially reversed the DNA damage phenotype caused by circ-ZNF609 depletion, and circ-ZNF609 depletion reduced the tumor size, tumor volume, and tumor weight through the miR-138-5p/SIRT7 axis in vivo." (PMID 35938040, 2022). "In this review, we aim to describe the biological roles and molecular mechanism of circ‐ZNF609 in tumour and other diseases and further explore its diagnostic, prognostic and therapeutic value." (PMID 34697887, 2021). "To further investigate the effect of Circ-ZNF609, we also created a nude mouse model with a primary tumor." (PMID 38472174, 2024). "A mouse xenograft tumor bearing model was developed to explore the carcinogenic consequences of Circ-ZNF609 in vivo." (PMID 38472174, 2024). "In conclusion, our findings indicate that exosomal Circ-ZNF609 from ESCC cells plays a significant role in promoting tumor growth, metastatic niche formation, and distant metastasis." (PMID 38472174, 2024). "The data showed that the silencing of circ-ZNF609 suppressed TP cell proliferation, migration and invasion and restrained tumor growth in xenograft mouse model." (PMID 35135416, 2022). "The experiments in vivo showed that circ-ZNF609 facilitated tumor growths, confirming the findings in vitro." (PMID 35938040, 2022). "In routine, it promoted the expression of polo-like kinase-1 (PLK1) by competitively binding to miR-1224-3p, and circ-ZNF609 also promoted tumor growth in vivo." (PMID 35938040, 2022). "The overexpression of circ-ZNF609 leads to increased tumor growth, while knockdown led to contrasting effects in mouse xenograft models." (PMID 35938040, 2022). "The immunohistochemistry assay showed that Ki-67 expression was reduced in tumor tissues of nude mice treated with sh-circ-ZNF609." (PMID 35135416, 2022). "Concurrently, LRRC1 overexpression significantly enhanced tumor cell proliferation, migration and invasion, while knockdown of circ-ZNF609 partially inhibited these inhibitory effects." (PMID 34898474, 2021). "Simultaneously, in vivo experiments showed that knockout of circ‐ZNF609 inhibited tumour growth and metastasis in mice." (PMID 34697887, 2021). "Wound healing and transwell assays showed that silencing circ-ZNF609 impaired the migration and invasion efficiency of tumor cells." (PMID 34898474, 2021). "Next, tumorigenicity analysis in the nude mice injected with U251 cells showed that the silencing of ZNF609 by siRNA obviously attenuated the tumor growth of U251 cells in the nude mice." (PMID 34520391, 2021). "Here, we review the biogenesis and function of circRNAs and the functional roles and molecular mechanism related to circ‐ZNF609 in neoplasms and other diseases." (PMID 34697887, 2021). "It was further found that the effect of circ‐ZNF609 on tumour cells was mainly realized through the circ‐ZNF609/miR‐342‐3p/RAP2C regulatory axis." (PMID 34697887, 2021). "The results of tumor xenograft assay also suggested that exogenous silencing of circ-ZNF609 inhibited tumor growth." (PMID 34898474, 2021). "We then looked at circ-ZNF609 expression in primary tumor biopsies obtained from 11 patients with RMS (6 ERMSs and 5 ARMSs), compared with skeletal muscle biopsies from three age-matched healthy donors." (PMID 30670781, 2019). "However, exosomal Circ-ZNF609, particularly in hypoxic exosomes, enhanced vascular density, which alleviated hypoxia at the local site and fostered tumor growth." (PMID 38472174, 2024). "As a carcinogen, circ-ZNF609 was abnormally upregulated in tumor tissues and cell lines." (PMID 35938040, 2022). "Moreover, miR-514a-5p silencing reversed the effects of circ-ZNF609 silencing on TC cell growth and metastasis, as well as tumor growth." (PMID 35135416, 2022). "Circ-ZNF609 silencing decreased the glucose uptake and lactate product of tumor cells, and overexpression of circ-ZNF609 could increase the radioresistance of cells." (PMID 35938040, 2022).